LHB (luteinizing hormone subunit beta)
Description:
Promotes spermatogenesis and ovulation by stimulating the testes and ovaries to synthesize steroids.
Synonyms: LSH-B; LSH-beta; CGB4; hLHB; HH23
Tractability: Antibody: its Gene Ontology location is reachable by antibodies, with high confidence; UniProt places it where antibodies can reach, with medium confidence; UniProt predicts a signal peptide or a membrane-spanning region.
Gene: Protein-coding gene on chromosome 19 (49,015,980 to 49,017,091, reverse strand). Ensembl gene ENSG00000104826.
Subcellular location: Secreted
Pathways (Reactome):
Metabolism: Androgen biosynthesis; Mineralocorticoid biosynthesis
Metabolism of proteins: Glycoprotein hormones; Reactions specific to the complex N-glycan synthesis pathway
Signal Transduction: G alpha (s) signalling events; Hormone ligand-binding receptors
Gene Ontology:
Molecular function: protein binding; hormone activity; signaling receptor binding
Biological process: cell-cell signaling; hormone-mediated signaling pathway; luteinizing hormone signaling pathway; male gonad development; ovarian follicle development; progesterone biosynthetic process; signal transduction; cell communication; signaling
Cellular component: extracellular region; Golgi lumen; pituitary gonadotropin complex
Genetic constraint (gnomAD): Loss-of-function variants: 11 observed, 11.21 expected, observed/expected ratio (o/e) 0.98, 90% interval 0.62 to 1.6. The upper end of that interval is the gene's LOEUF score, 1.6, which puts it in group 6 of 6, group 1 being the genes least tolerant of losing a copy. Missense variants: 184 observed, 200.74 expected, observed/expected ratio (o/e) 0.92, 90% interval 0.81 to 1.04. Synonymous variants: 86 observed, 83.47 expected, observed/expected ratio (o/e) 1.03, 90% interval 0.87 to 1.23.
Homologues: Orthologues: chimpanzee LHB (96% identical), macaque CGB8 (83% identical), Drosophila melanogaster Gpb5 (16% identical). Paralogues in human: CGB3 (82% identical), CGB5 (82% identical), CGB7 (82% identical), CGB8 (82% identical), CGB2 (80% identical), CGB1 (79% identical), TSHB (36% identical), FSHB (32% identical), GPHB5 (26% identical).
Diseases named in the same sentence as LHB in open-access papers:
LHB is named in the same sentence as 62 diseases in open-access papers, as found by Europe PMC text mining. Sharing a sentence is not in itself a finding about the gene and the disease. The quoted sentences say what the papers report.
depression (114 papers, 2009 to 2025). "Evidence from both human 9-11 and animal studies demonstrated hyperactivity and synaptic remodeling in LHb associated with the onset of major depression-like symptoms following stress 7, 8, 12-15." (PMID 39897557, 2025). "LHb hyperactivity has been implicated in the pathophysiology of depression, but the electrophysiological mechanisms underlying this hyperactivity remain poorly understood." (PMID 40168081, 2025). "Although considerable evidence implicates the LHb in the pathogenesis of major depression, the underlying molecular mechanisms that drive hyperexcitation within this brain region remain ill defined." (PMID 39897557, 2025). "Unsurprisingly, the LHb has been implicated as an important node in the pathophysiology of depression in rodents, rhesus macaques, and humans (Matsumoto and Hikosaka, 2007; Sartorius and Henn, 2007; L-M." (PMID 39689968, 2025). "Given that LHb burst firing has been strongly linked with depression, their findings provide new insights into LHb and potentially point to burst-firing patterns as potential targets for neuropathic pain therapies." (PMID 40263415, 2025). "LHb overactivity has been associated with chronic stress-induced anxiety and depression in animal models of anxiety and depression, as well as in patients with depression." (PMID 39605808, 2024). "The LHb is implicated in human disorders, including depression, schizophrenia and substance abuse, and in animal models." (PMID 38177339, 2024). "The LHb has been implicated in depression-related behavior, but preclinical and clinical evidence suggest that it also plays a role in stress-induced anxiety-related behavior." (PMID 39086371, 2024). "For example, LHb activation inhibits the mPFC, which controls social competitiveness and reinforces retreating behavior in contests, leading to a depression-like state associated with a loss of social status." (PMID 38493173, 2024). "The LHb, implicated in various animal models of depression, consistently exhibits increased activity and is associated with psychiatric disorders, particularly major depression." (PMID 39273641, 2024). "A molecule implicated in LHb hyperactivation in an animal model of depression, referred to as p11, successfully restored mEPSCs as well as burst firing patterns in a chronic stress model, contributing to the recovery of depressive behaviors in animals." (PMID 38193032, 2023). "These advances will aid in the development of novel interventions for neuropsychiatric conditions that have been linked to LHb dysfunction such as depression, anxiety, and addiction." (PMID 35308564, 2022). "Whilst we focused on the LHb in the present study, other brain regions are also implicated to have key roles in depression-like behaviour including the hippocampus and the prefrontal cortex." (PMID 34888704, 2022). "LHb has been widely reported to be strongly associated with depression and has emerged as a crucial determinant of the pathogenesis of depression." (PMID 36386995, 2022). "The fourth area that we will consider is the LHb, an area that has been implicated in anxiety, stress, pain, avoidance learning, attention, human reward processing, psychosis and depression." (PMID 33994933, 2021). "Although a possible involvement of the habenula NPY-Y1 signaling in sexual and social behavior is not well known, NPY has been implicated in stress-related responses such as anxiety and depression, which are closely associated with LHb dysfunction." (PMID 35221943, 2021). "Since the LHb is a core brain region implicated in depression that mediates avoidance behavior, it is likely that it also mediates the withdrawal of motivation to obtain reward as observed in LHPBN-activated mice." (PMID 33962958, 2021). "On the other hand, studies involving humans and rodent models of helplessness have suggested that an over-reactivity of the LHb can induce symptoms associated with depression (dark purple arrows)." (PMID 33962969, 2021).
depression (continued). "Hyperexcitability and dysfunction of the LHb have been implicated in the development of psychiatric disorders including depressive disorder and bipolar disorders." (PMID 34251338, 2021). "The LHb has been implicated in the processing of emotional valence, depression, and withdrawal from drugs of abuse." (PMID 32341122, 2020). "In animals, inhibition of LHb activity is associated with depression-like behaviors and stimulation of LHb shows antidepressant-like activity." (PMID 32561573, 2020). "Our previous study used prior knowledge to localize the etiological origin of depression (lateral habenula, LHb), selected discriminate connections linked with LHb, and realized an accurate prediction of subclinical depression." (PMID 33505236, 2020). "As reviewed in this article, both depressive disorders and alcohol use disorders can cause LHb hyperactivity, which inhibits the activity of dopamine neurons and serotonin neurons in the midbrain reward center." (PMID 33143210, 2020). "The diminishment of both drives is characteristic of the anhedonia observed in major depressive disorder (MDD), and LHb hyperactivation has been associated with both the neurobiologic dysregulation and the motivational symptoms of depression." (PMID 33141766, 2020). "Consistent with our findings, a recent study demonstrated that ketamine blocks LHb neuronal bursting that underlies behavioral depression and anhedonia in two rodent animal models of depression through local NMDAR-dependent blockade in the LHb." (PMID 30425634, 2018). "Recent evidence has demonstrated that hyperactivity of the LHb is implicated in the pathogenesis of depression." (PMID 30356828, 2018). "It is important to state, however, that the underlying mechanisms leading to LHb hyperactivity in the LH and the maternal separation models of depression are different." (PMID 30083090, 2018). "On the other hand, the LHb is composed principally of excitatory projection neurons and multiple studies show that LHb activity relates to and drives behaviors linked to aversion, depression, or disappointment." (PMID 29487284, 2018). "In animal models and patients with depression, the inhibition of the LHb can cause remission in both the rats’ depression-like behaviors and patients’ depressive symptoms." (PMID 28270756, 2017). "The LHb has also been linked to major depressive disorder (MDD) in both preclinical and clinical research." (PMID 24734015, 2014). "Taken together, accumulating evidences from the animal and human studies suggested that hyperactivated LHb is associated with symptoms in depression." (PMID 24339810, 2013). "Additionally, aberrant LHb activity is associated with selective features of major depression such as learned helplessness 12, 16 and anhedonia 17, which are observed in parallel with upregulated neuronal activity specifically within the LHb." (PMID 39897557, 2025). "Notably, acute stress alters LHb's response, turning reward signals into ones resembling punishment, which is linked to depression." (PMID 39120643, 2025). "Rationale: The hyperactivity of lateral habenula (LHb) has been implicated in the pathophysiology of depression, but the regulatory mechanisms of inhibitory synapses in this context remains unclear." (PMID 39897557, 2025). "Yang and colleagues have linked these rebound bursts with depressive disorder, compatible with our hypothesis that the VP to LHb pathway contributes to DMN regulation." (PMID 41323281, 2025). "Moreover, LHb is able to receive feedback signals from the hypothalamus, and potentiation of these synaptic connections can cause depression under stress conditions." (PMID 39596543, 2024). "Increased activity and βCaMKII expression in LHb were found to impact the serotonin (5-HT) neuronal activity in the DRN, providing a potential neurobiological link through which LHb contributes to the development of depression-like behaviors in illnesses associated with chronic pain." (PMID 39273641, 2024).
depression (continued). "Additionally, cellular and synaptic mechanisms that promote the activity of LHb glutamatergic neurons have been linked to depressive-like behaviors in animal models, despite well-documented sex differences in major depressive disorder in clinical reports." (PMID 38654275, 2024). "LHb aberrant activity (specifically hyperactivity) is also linked to depression." (PMID 38106086, 2023). "Thus, researchers have gradually recognized the LHb as a crucial regulator of pain and associated experiences of anxiety and depression." (PMID 36187288, 2022). "Another pathway underlying this disorder is the LHb’s increased excitation of raphe inhibitory interneuron-based inhibition of serotonergic neurons, which causes a passive coping transition, a marker of depression." (PMID 35444521, 2022). "Given the LHb’s role in processing stimuli of negative valence, it is intriguing to speculate that increased LHb streamline number may contribute to susceptibility to depression." (PMID 35784832, 2022). "This peculiar connectivity of the LHb might predispose people to depression or, alternatively, some life events could promote behavioral patterns leading to that phenotype." (PMID 33962969, 2021). "We therefore suggest that the enhanced activity of the LHb-DRN pathway may not only be involved in the pathogenesis of depression, but it also represent an important underlying mechanism for the development of chronic pain." (PMID 28270756, 2017). "In addition, the LHb has been linked to major depression, while the MHb has been linked to the effects of nicotine." (PMID 24734015, 2014). "Consistent with this conjecture, high LHb activity has been linked with depression." (PMID 24133441, 2013). "In addition to its role in the reward system, the LHb has been implicated in a number of related functions, including depression and pain sensitivity." (PMID 22485164, 2012). "In this work we have implemented the maternal separation model of depression, in tandem with behavioural assays and in vitro electrophysiological recording techniques to dissect how early life stress influences the behavioural state and the underlying physiology of the LHb in adult mice." (PMID 36371544, 2023). "Indeed, the LHb has been implicated in anhedonia, learned helplessness, and rumination which have all been linked to hopeless depression and suicidality in past literature." (PMID 35359586, 2022). "A study on depression models discovered that glutamatergic LHb neurons that project to the VTA receive increased dopaminergic inputs, potentially causing aversion and affecting cognitive functions in major depression." (PMID 39120643, 2025). "Given the importance of these processes to psychiatric conditions, understanding how LHb activity impacts cognitive function allows novel insights into the neurobiological mechanisms of disorders like depression." (PMID 40799491, 2025). "Lowering βCaMKII levels or inhibiting its activity can alleviate depression symptoms, making βCaMKII vital for LHb function and a significant factor in depression." (PMID 41378345, 2025). "The LHb, a brain region involved in depression, plays a key role in processing both reward and punishment." (PMID 39120643, 2025). "The LHb is known to participate in stress-induced behavior and learning, and overactivation of the LHb was observed in patients with major depressive disorder." (PMID 39560766, 2025). "As for this circuit function, they demonstrated that inhibiting the 5-HTDRN → SOMCeA → LHb pathway produces depression-like behavior, whereas its activation alleviates pain and depression-like symptoms." (PMID 39120643, 2025). "To explore these questions, we combined genetic manipulations of MDGA1/Nlgn2 with functional assessment of LHb synapses in mice subjected to restraint stress and subsequent biobehavioral assays for depression." (PMID 39897557, 2025). "As recently unveiled, LHb-raphe nucleus function was recognized to play a role in the pathogenesis of depression." (PMID 40337515, 2025).
depression (continued). "LHb neurons also send projections to different downstream regions, such as dorsal raphe, to modulate the serotonergic system and depression-related behavioral phenotypes." (PMID 38654275, 2024). "This study has revealed that the modulation of the LHb brain region can improve depression-like behavior in mice, consequently enhancing the process of wound healing." (PMID 38440257, 2024). "In the literature, the LHb has been reported as being involved in pain processing, stress, depression, and pain-related depression." (PMID 37987455, 2023). "The LHb regulates negative emotions, and evidence from clinical studies and animal models suggests that the LHb exhibits hyperactivity in major depressive disorder." (PMID 36756128, 2023). "Li and colleagues showed that when this stress model was combined with inflammatory pain (formalin injection), the LHb activity was even higher, suggesting a synergistic effect between depression and pain." (PMID 37987455, 2023). "Mounting evidence from animal and human studies indicates that hyperactivity of the LHb plays a critical role in depression etiology." (PMID 37261976, 2023). "Re-exposure to stress results in the reappearance of LHb hyperactivity offering a possible mechanism to explain how depression relapses occur following previous depressive episodes." (PMID 36371544, 2023). "Conversely, inhibition of LHb activity through inhibitory inputs or diminished excitatory drive reduces behavioral anxiety and depression, and promotes positive reinforcement." (PMID 35972745, 2023). "It is now very well established that the enhanced activity of the LHb is critical in patients and animal models of depression." (PMID 38193032, 2023). "Specifically, the LHb becomes hyperactive in depression, thus enhancing output to the midbrain reward circuitry, for which the LHb acts as an inhibitory modulator." (PMID 36371544, 2023). "Circuit-specific studies focusing on specific projecting areas, such as the ventral tegmental area, dorsal raphe nucleus, and hypothalamus have provided well-established insights into the LHb’s involvement in animal models of depression." (PMID 38193032, 2023). "Chronic stress creates a marked increase in LHb activity and increased LHb activity promotes depression-related behavior." (PMID 35359586, 2022). "Pharmacological and optogenetic manipulation of the LHb activity alters DAergic regulation of mPFC neuronal activity, which controls multiple brain processes that are relevant to depression." (PMID 36059987, 2022). "The LHb plays an important role in the development of depression and anxiety and has a large distribution of estrogen β receptors." (PMID 35615566, 2022). "The LHb is hyperactivated during depression, and recent findings suggest a potential contribution of local glial cells." (PMID 35990593, 2022). "Herein, we systematically combed advances from rodents, summarized changes in the LHb and related neural circuits in depression, and attempted to analyze the intrinsic logical relationship among these pathological alterations." (PMID 36386995, 2022). "Quantitative proteomic screens show that LHb expression of the β form of calcium/calmodulin-dependent protein kinase type II (βCaMΚΙΙ) is up-regulated in animal models of depression and down-regulated by antidepressants." (PMID 36059987, 2022). "Studies have shown that the lateral habenula (LHb) has an important relationship with the pathogenesis of depression." (PMID 36064380, 2022). "Excessive LHb activity can also lead to impaired motivated behavior and result in the pathophysiology of depression." (PMID 35444521, 2022). "Research has also indicated that the NMDARs of LHb neurons are involved in the regulation of depression." (PMID 36187288, 2022). "The LHb plays an important role in the pathogenesis of anxiety and depression and is a key site for controlling neuronal activity in the DRN and VTA." (PMID 35615566, 2022).